USF1 (upstream transcription factor 1)
Diseases named in the same sentence as USF1 in open-access papers (continued):
Sharing a sentence is not in itself a finding about the gene and the disease.
atherosclerosis (continued). "USF1 inhibition has been demonstrated to ameliorate hyperlipidemia, adiposity, and atherosclerosis in mice, suggesting USF1 as a potential therapeutic target for atherosclerosis." (PMID 38424494, 2024). "Our study firstly reported that USF1 facilitated atherosclerosis development via inducing EndMT." (PMID 38424494, 2024). "So far, the detailed mechanisms through which USF1 affects atherosclerosis progression are largely unknown, which deserve further investigation." (PMID 38424494, 2024). "USF1 participates in the transcriptional modulation of multiple genes, which serves as a crucial regulator of a series of disorders, such as cancer, diabetes, as well as atherosclerosis." (PMID 38424494, 2024). "Because increased uptake of modified LDL by macrophages promotes the generation of cholesterol-loaded foam cells, an early sign of atherosclerosis, we next examined whether expression of USF1 has an effect on cholesterol accumulation in macrophages." (PMID 30545366, 2018). "We recently demonstrated that low USF1 expression in mice and humans associates with high plasma HDL-C and low triglyceride levels, as well as protection against obesity, insulin resistance, and atherosclerosis." (PMID 30545366, 2018). "The genetic variation in USF1 influence USF1 transcript expression in advanced atherosclerosis and regulates levels and metabolism of circulating apoB and apoB-containing lipoprotein particles in sex-dependent manner, but is not a major determinant of early markers of atherosclerosis." (PMID 24722012, 2014). "Finally, USF1 knockdown delayed atherosclerosis progression via inhibiting EndMT in mice." (PMID 38424494, 2024). "Thus, USF1 exacerbated atherosclerosis progression by transcriptional activation of USP14." (PMID 38424494, 2024). "Therefore, USF1 may be involved in atherosclerosis by regulating the expression of IL-1β, VEGF, TNF-α, and IL-6." (PMID 35783856, 2022). "Strikingly, absence of USF1 function in bone marrow-derived cells was associated with exacerbated blood leukocyte (+ 100%; P < 0.01) and peritoneal leukocyte (+ 50%; P < 0.05) lipid loading and an increased atherosclerosis susceptibility (+ 31%; P < 0.05)." (PMID 34385562, 2021). "The atheroprotective role of USF1 deficiency was also observed in humans, in whom individuals having a USF1 mRNA expression reducing allele displayed elevated HDL-C and reduced triglyceride levels, as well as reduced atherosclerosis in coronary arteries, also featuring fewer calcified plaques." (PMID 30545366, 2018). "Further research investigated the genetic interaction between USF1 and APOA5, revealing their combined influence on lipid levels and atherosclerosis progression." (PMID 40507612, 2025). "In this study, we demonstrated that USF1 transcriptionally activated USP14 to restrain NLRC5 degradation, which prompted atherosclerosis by facilitating EndMT by activation of Smad2/3 pathway." (PMID 38424494, 2024). "Of note, as predicted by JASPAR database, USF1 can directly bind to USP14 promoter, providing possibility that USF1 might influence atherosclerosis progression via transcriptional modulation of USP14." (PMID 38424494, 2024). "USF1 gene was studied because USF1 protein regulates the transcriptional activation of a variety of genes involved in glucose, lipid and apolipoproteins (APOCIII, APOAII and APOE) metabolism in the development of atherosclerosis." (PMID 23593297, 2013).
melanoma (11 papers, 2014 to 2025). A malignant, usually aggressive tumor composed of atypical, neoplastic melanocytes. "Thus, cell proliferation is maintained inappropriately in Usf1 KO mice and in USF1-deficient melanoma cells challenged by genotoxic stress." (PMID 24831529, 2014). "The poorly expressed ventricular zone expressed PH domain-containing 1 (VEPH1) and up-regulated upstream transcription factor 1 (USF1) in melanoma tissues promoted EMT." (PMID 35461253, 2022). "Here we demonstrate that ILEI is an in vivo regulator of melanoma invasiveness and is transcriptionally up-regulated by the upstream stimulatory factor-1 (USF-1), an E-box–binding, basic-helix-loop-helix family transcription factor." (PMID 29871931, 2018). "For instance, USF1 silencing was identified to inhibit EndMT in melanoma cells." (PMID 38424494, 2024). "However, in contrast to the results presented here the sub‐cellular localization of the acetylated‐phosphorylated USF‐1 remained nuclear in melanoma cells." (PMID 34533293, 2022). "This would potentially include MITF, a key regulator of melanocyte and melanoma biology, or USF1/2." (PMID 34819350, 2021). "In summary, our work reveals that ILEI contributes to melanoma cell invasiveness in vivo without affecting primary tumor growth and is transcriptionally up-regulated by USF-1." (PMID 29871931, 2018). "In addition, DMPB induced levels of USF1 and DMPB-mediated melanin synthesis was dependent on USF1 like melanoma cells." (PMID 26535571, 2015). "A study describing that USF1 is involved in the UV stress response in COS7 and B16 melanoma cells was the first showing that not JNK but the stress-responsive p38α acts as an USF1-phosphorylating kinase." (PMID 25741280, 2015). "In our study, DMF reversed melanoma resistance to NKmK, reducing MHC II expression without affecting upstream IFNγ targets (USF1, IRF1, IRF2)." (PMID 41078003, 2025).
Obesity (10 papers, 2017 to 2024). Accumulation of substantial excess body fat. "Total body upstream stimulatory factor 1 (USF1) deficiency in mice is associated with brown adipose tissue activation and a marked protection against the development of obesity and atherosclerotic lesions." (PMID 34385562, 2021). "Considering that Kbtbd11 is a target USF1 gene that regulates proliferation and differentiation in adipocytes, genetic variation in USF1 and varying Kbtbd11 expression levels could be associated with obesity." (PMID 31844712, 2019). "In addition, the genetic variants of USF1 are associated with familial combined hyperlipidemia, increased risk of cardiovascular diseases, risk of type 2 diabetes, metabolic syndrome traits, and increased levels of obesity." (PMID 31844712, 2019). "Cell biology; Cell Differentiation; Gene Expression; Gene Regulation; Transcription Factor; Biochemistry; Molecular Biology; Obesity; Kbtbd11; 3T3-L1 differentiation; USF1; transcriptional regulation." (PMID 31844712, 2019). "Concordant with several metabolic traits identified in the PheWAS such as obesity and cholesterol levels, the QTL analyses identified two genes, PNPLA2 and USF1, whose functions are directly connected to those traits." (PMID 34027315, 2021). "Top findings within the block involved well-known obesity genes such as the FTO, the CYP19A1 and the USF-1." (PMID 31527397, 2019). "Further study of how PASK is regulating the many activities of USF1 may provide additional insight into the role of PAS kinase in human diseases including hyperlipidemia, obesity and diabetes." (PMID 30381292, 2019).
hepatocellular carcinoma (9 papers, 2009 to 2023). A malignant tumor that arises from hepatocytes. "Interestingly, we also detected a significant increase of ABCA1 protein in human hepatoma cells subjected to USF1 knock-down (HuH7)." (PMID 30545366, 2018). "We have shown here that oleate increases the nuclear abundance of USF1 in human hepatoma cells." (PMID 22253973, 2009). "In hepatoma cells, expression of ADAMTS1 is regulated differentially by SP1 (specificity protein 1) and USF1 (upstream stimulatory factor 1) under normoxic and hypoxic conditions." (PMID 29212212, 2017). "The USF1 element in Cdc2 described in A549 epithelial cell line derived from a lung carcinoma tissue-, H1-hESC embryonic stem cells and HepG2 hepatocellular carcinoma was in the region +1044 to +1300 from the TSS, differently positioned from what we found for USF1 recruitment." (PMID 24859236, 2014). "According to a recent study, the TF USF1, a SE component, drove the expression of the long noncoding RNA (lncRNA) FASRL in hepatocellular carcinoma (HCC)." (PMID 37501079, 2023).
lung carcinoma (9 papers, 2014 to 2024). "Recent studies have found that USF1 is involved in regulating the development of multiple type of tumors, including lung cancer." (PMID 35155573, 2022). "USF1-related studies have shown that USF1 can transcriptionally upregulate the expression of FAK in lung cancer, thus activates the FAK signaling pathway and promotes cell migration." (PMID 34876062, 2021). "The data indicate that USF1 can bind to the TGF-β1 promoter to increase its transcriptional activity in lung cancer cells." (PMID 32144580, 2020). "Actually, the oncogenic effects of USF1 in lung cancer have been previously reported." (PMID 35155573, 2022). "Collectively, these results suggest that knockdown of ERK5 may suppress EMT in lung cancer cells and subsequent metastasis, which is likely to occur because of its regulation of USF1." (PMID 32144580, 2020). "The activities of SP‐1 and STAT3 induced by NF‐κB, USF1, and IL‐6 were not significantly affected by K284 treatment, but lipopolysaccharide‐ and TNF‐α‐induced SP‐1, STAT3, and AP‐1 were significantly decreased by K284 treatment in A549 lung cancer cells." (PMID 34758182, 2022).
dyslipidemia (8 papers, 2009 to 2024). "USF1 polymorphisms have been associated with increased risk for type 2 diabetes and metabolic syndrome." (PMID 32847508, 2020). "The USF1 gene has previously been associated with a common dyslipidemia, FCHL." (PMID 19750004, 2009). "Dyslipidemias were excluded from these analyses because of the impact of USF1 gene on serum lipid levels." (PMID 26068452, 2015). "However, in these studies, the effect of USF1 was more pronounced in subjects already diagnosed with CAD, FCHL, diabetes and metabolic syndrome." (PMID 24722012, 2014).
gastric cancer (8 papers, 2019 to 2025). A primary or metastatic malignant neoplasm involving the stomach. "Studies of human ovarian cancer and murine Helicobacter pylori driven gastric cancer both showed cytoplasmic localization of USF1." (PMID 40658711, 2025). "In this study, we highlight the relevance of SOX2 in the behavior of gastric cancer but there are other molecular players, such as the recently identified USF1 whose interaction with the CSC phenotype needs to be addressed." (PMID 32093282, 2020). "Further assays testified that LOXL1‐AS1 maintained CSC properties and induced gastric cancer tumorigenesis by targeting miR‐708‐5p/USF1 pathway." (PMID 31468594, 2019). "Our results illustrated that LOXL1‐AS1 regulated USF1 to execute its oncogenic activities in gastric cancer through sponging miR‐708‐5p, which opened a novel prospective for the therapeutic regimens of patients with gastric cancer." (PMID 31468594, 2019). "Our study unravelled that LOXL1‐AS1/miR‐708‐5p/USF1 pathway contributed to the development of gastric cancer." (PMID 31468594, 2019). "Rescue experiments testified the stimulative role of LOXL1‐AS1/miR‐708‐5p/USF1 pathway in gastric cancer progression." (PMID 31468594, 2019). "Namely, described results affirmed that LOXL1‐AS1 maintained stemness and accelerated gastric cancer deterioration via miR‐708‐5p/USF1." (PMID 31468594, 2019). "In view of the fact that the oncogenic role of USF1 has been reported in diverse cancers, we explored the expression of USF1 in gastric cancer tissues and cells." (PMID 31468594, 2019). "RT‐qPCR analysis showed that USF1 expressed at a higher level in gastric carcinoma samples compared to corresponding normal specimens." (PMID 31468594, 2019). "Moreover, the expression of USF1 in gastric cancer was higher than in normal control and LOXL1‐AS1 negatively modulated USF1." (PMID 31468594, 2019). "Similarly, the remarkable upregulation of USF1 was observed in gastric cancer cells." (PMID 31468594, 2019). "Mechanically, LOXL1‐AS1 exerted its performance through modulation of miR‐708‐5p/USF1, which provided a better understanding of LOXL1‐AS1‐mediated gastric cancer progression." (PMID 31468594, 2019).
hyperlipidemia (8 papers, 2008 to 2024). "The human homolog of Cbf1, USF1, has been associated with lipid biogenesis and hyperlipidemia in many studies." (PMID 30381292, 2019). "Other variants of USF1 have also been reported as showing significant gender-genotype interaction for triglycerides and BMI in familial combined hyperlipidemia families." (PMID 18974842, 2008). "Its human homolog, Upstream transcription factor 1 (USF1), is a key regulator of genes involved in lipid homeostasis and USF1 mutations are strongly correlated with hyperlipidemia." (PMID 30381292, 2019).
diabetes (7 papers, 2014 to 2025). "Thus, USF1 activation with high-glucose stimulation in diabetes mellitus enhances gene expression of TGF-β1 that induces an accumulation of ECM, inflammation and glomerular sclerosis in kidney." (PMID 33947045, 2021). "It is considered that the activation of the TGF-β1 promoter by AP-1 transcription factor binding is not specific for diabetic nephropathy, whereas the transcription factor USF1 is specifically activated by high-glucose stimulation in diabetes mellitus and activates the TGF-β1 promoter." (PMID 33947045, 2021). "Hyperglycemia induces translocation of USF1 from cytoplasm to nucleus in diabetes mellitus." (PMID 33947045, 2021). "In addition, increased USF1 in diabetes mellitus also binds to the promoter of osteopontin, which induces mesangial proliferation that leads to glomerular hypertrophy." (PMID 32093382, 2020). "Finally, USF-1-mediated regulation of WBP2 in response to insulin stimulation raises the possibility of WBP2’s involvement in insulin signaling-related diseases such as insulin resistance and diabetes." (PMID 32393834, 2020).
asthma (6 papers, 2014 to 2025). "For the rs10905284 (GATA3), the asthma risk allele (C; proxy rs3802597; r2=0·93) had an effect on upstream stimulatory factor 1 (USF1) and 2 (USF2) binding in various cell types, including airway epithelium." (PMID 30552067, 2019). "By searching PubMed, NFKB1, STAT6, E2F1, USF1, and CBFB were the verified asthma-related TFs, while NFKB1 and STAT6 were the newly discovered asthma-related genes in 2013." (PMID 24790987, 2014).
prostate carcinoma (6 papers, 2012 to 2025). A carcinoma that arises from epithelial cells of the prostate gland. "Through unbiased proteomics screening, we reveal that the risk allele A of rs4519489 exhibits enhanced binding to USF1, a novel oncogenic transcription factor (TF) implicated in prostate cancer progression and prognosis, resulting in elevated NOL10 expression." (PMID 38645058, 2024). "The concurrent expression of NOL10 and USF1 correlates with aggressive prostate cancer characteristics and poorer prognosis." (PMID 38645058, 2024). "The identification of USF‐1 as a putative target for reversing the radioresistance by HDAC inhibitors has opened a new paradigm for prostate cancer therapy." (PMID 34533293, 2022). "The aim of this study was to investigate the role of upstream stimulatory factor‐1 (USF‐1) in the induction of radioresistance in prostate cancer and its targeting by histone deacetylase (HDAC) inhibitors to reverse resistance." (PMID 34533293, 2022). "This suggests that USF‐1 can contribute towards the radioresistance in prostate cancer as demonstrated by the overexpression studies." (PMID 34533293, 2022). "Further study indicated that hypomethylation of the SINE Alu region of the MIEN1 promoter and upstream stimulatory factor 1 (USF1) binding triggered MIEN1 expression in prostate cancer in vitro and in vivo." (PMID 31581708, 2019). "Among these six, HLF, JUN, c-MYC, EGR1, SMAD1, and HIF1A, were also identified as PTEN-controlled TFs, and four, ESR2, MYB, RELA, and USF1, as prostate cancer-related TFs." (PMID 22347425, 2012). "Furthermore, pre‐clinical studies in animal tumor models and tumor types other than prostate cancer will further enhance our understanding of role of USF‐1 as a mediator of radioresistance." (PMID 34533293, 2022). "In PC-3 human prostate cancer cells, HDAC inhibition blocked the nuclear accumulation of USF1 induced by ionizing radiation, leading to downregulation of USF1 target genes." (PMID 40658711, 2025). "Future studies that will further help in understanding the role of USF‐1 in IR and HDAC inhibitors‐induced signaling in other prostate cancer cells will lead to development of better drugs and treatment strategies for cancer therapy." (PMID 34533293, 2022). "Therefore, this study was aimed to understand the regulatory roles of radiation‐induced USF‐1, its targeting by HDAC inhibitors, and to identify the novel mechanisms underlying the reversal of radioresistance, leading to radiosensitizing effects of these inhibitors in prostate cancer cells." (PMID 34533293, 2022).
colon carcinoma (4 papers, 2010 to 2021). "We found that the colon cancer cell lines HCT-116 and HCT-15 exhibited a confluence-dependent increase in CD26 mRNA and protein, associated with decreased expression of c-Myc, increased USF-1 and Cdx 2 levels, and unchanged HNF-1α expression." (PMID 21284881, 2011). "Luciferase assays sustained a role for USF1/2 and HNF1-alpha in UGT1A1 regulation in colon cancer cells." (PMID 20096102, 2010).
coronary artery disease (4 papers, 2010 to 2022). "Association of the USF1 gene haplotypes with coronary artery disease." (PMID 26068452, 2015). "The frequency of genotypes and alleles of the USF1 gene polymorphisms in the groups of coronary artery disease (CAD) patients and blood donors." (PMID 26068452, 2015). "Knockout studies of USF1 in mice have been shown to enhance cholesterol efflux in macrophages and downregulate secretion of pro-inflammatory cytokines such as MCP-1 and IL-1β and USF1 variants in humans have been associated with familial combined hyperlipidemia and coronary artery disease." (PMID 34027315, 2021).